SFPQ (splicing factor proline and glutamine rich)
Description:
DNA- and RNA binding protein, involved in several nuclear processes. Essential pre-mRNA splicing factor required early in spliceosome formation and for splicing catalytic step II, probably as a heteromer with NONO. Binds to pre-mRNA in spliceosome C complex, and specifically binds to intronic polypyrimidine tracts. Involved in regulation of signal-induced alternative splicing. During splicing of PTPRC/CD45, a phosphorylated form is sequestered by THRAP3 from the pre-mRNA in resting T-cells; T-cell activation and subsequent reduced phosphorylation is proposed to lead to release from THRAP3 allowing binding to pre-mRNA splicing regulatotry elements which represses exon inclusion. Interacts with U5 snRNA, probably by binding to a purine-rich sequence located on the 3' side of U5 snRNA stem 1b. May be involved in a pre-mRNA coupled splicing and polyadenylation process as component of a snRNP-free complex with SNRPA/U1A. The SFPQ-NONO heteromer associated with MATR3 may play a role in nuclear retention of defective RNAs. SFPQ may be involved in homologous DNA pairing; in vitro, promotes the invasion of ssDNA between a duplex DNA and produces a D-loop formation. The SFPQ-NONO heteromer may be involved in DNA unwinding by modulating the function of topoisomerase I/TOP1; in vitro, stimulates dissociation of TOP1 from DNA after cleavage and enhances its jumping between separate DNA helices. The SFPQ-NONO heteromer binds DNA. The SFPQ-NONO heteromer may be involved in DNA non-homologous end joining (NHEJ) required for double-strand break repair and V(D)J recombination and may stabilize paired DNA ends; in vitro, the complex strongly stimulates DNA end joining, binds directly to the DNA substrates and cooperates with the Ku70/G22P1-Ku80/XRCC5 (Ku) dimer to establish a functional preligation complex. SFPQ is involved in transcriptional regulation. Functions as a transcriptional activator. Transcriptional repression is mediated by an interaction of SFPQ with SIN3A and subsequent recruitment of histone deacetylases (HDACs). The SFPQ-NONO-NR5A1 complex binds to the CYP17 promoter and regulates basal and cAMP-dependent transcriptional activity. SFPQ isoform Long binds to the DNA binding domains (DBD) of nuclear hormone receptors, like RXRA and probably THRA, and acts as a transcriptional corepressor in absence of hormone ligands. Binds the DNA sequence 5'-CTGAGTC-3' in the insulin-like growth factor response element (IGFRE) and inhibits IGF1-stimulated transcriptional activity. Regulates the circadian clock by repressing the transcriptional activator activity of the CLOCK-BMAL1 heterodimer. Required for the transcriptional repression of circadian target genes, such as PER1, mediated by the large PER complex through histone deacetylation (By similarity). Required for the assembly of nuclear speckles. Plays a role in the regulation of DNA virus-mediated innate immune response by assembling into the HDP-RNP complex, a complex that serves as a platform for IRF3 phosphorylation and subsequent innate immune response activation through the cGAS-STING pathway.
Synonyms: PSF; PPP1R140; POMP100
Tractability: PROTAC: UniProt records ubiquitination sites on it; ubiquitination databases record sites on it; its protein half-life has been measured.
Gene: Protein-coding gene on chromosome 1 (35,176,378 to 35,193,446, reverse strand). Ensembl gene ENSG00000116560.
Subcellular location: Nucleus speckle; Nucleus matrix; Cytoplasm
Subcellular location (Human Protein Atlas): Nucleoplasm
Pathways (Reactome):
Disease: Suppression of apoptosis
Signal Transduction: PTK6 Regulates Proteins Involved in RNA Processing
Gene Ontology:
Molecular function: DNA binding; histone deacetylase binding; protein binding; protein homodimerization activity; RNA binding; chromatin binding; transcription cis-regulatory region binding; nucleic acid binding
Biological process: activation of innate immune response; alternative mRNA splicing, via spliceosome; double-strand break repair via homologous recombination; negative regulation of transcription by RNA polymerase II; positive regulation of oxidative stress-induced intrinsic apoptotic signaling pathway; positive regulation of transcription by RNA polymerase II; chromatin remodeling; mRNA processing; negative regulation of circadian rhythm; negative regulation of DNA-templated transcription; regulation of circadian rhythm; regulation of DNA-templated transcription; RNA splicing; dendritic transport of messenger ribonucleoprotein complex
Cellular component: chromatin; cytoplasm; nuclear matrix; nuclear speck; nucleoplasm; nucleus; paraspeckles; RNA polymerase II transcription regulator complex; cytosol; dendrite
Genetic constraint (gnomAD): Loss-of-function variants: 10 observed, 59.76 expected, observed/expected ratio (o/e) 0.17, 90% interval 0.1 to 0.28. The synonymous counts are far from expectation, so gnomAD's model fits this gene poorly and the ratio says little. Missense variants: 843 observed, 852.53 expected, observed/expected ratio (o/e) 0.99, 90% interval 0.93 to 1.05. Synonymous variants: 503 observed, 313.45 expected, observed/expected ratio (o/e) 1.6, 90% interval 1.49 to 1.73.
Cancer hallmarks: escaping programmed cell death (promotes)
Homologues: Orthologues: macaque SFPQ (99% identical), pig SFPQ (97% identical), dog SFPQ (97% identical), chimpanzee SFPQ (96% identical), mouse Sfpq (94% identical), rat Sfpq (94% identical), rabbit SFPQ (70% identical), tropical clawed frog sfpq (64% identical), zebrafish sfpq (52% identical), Drosophila melanogaster nonA (29% identical), Caenorhabditis elegans nono-1 (29% identical), Drosophila melanogaster nonA-l (28% identical), and 1 more. Paralogues in human: PSPC1 (40% identical), NONO (40% identical), SPEN (20% identical), RBM15 (13% identical), RAVER1 (12% identical), RBM15B (11% identical), RAVER2 (11% identical).
Diseases named in the same sentence as SFPQ in open-access papers:
SFPQ is named in the same sentence as 77 diseases in open-access papers, as found by Europe PMC text mining. Sharing a sentence is not in itself a finding about the gene and the disease. The quoted sentences say what the papers report.
amyotrophic lateral sclerosis (18 papers, 2018 to 2025). Amyotrophic lateral sclerosis (ALS) is a neurodegenerative disease characterized by progressive muscular paralysis reflecting degeneration of motor neurons in the primary motor cortex, corticospinal tracts, brainstem and spinal cord. "This growing body of evidence suggests that SFPQ is significantly implicated in various neurodegenerative disorders, such as amyotrophic lateral sclerosis (ALS), frontotemporal lobar degeneration (FTLD), and AD." (PMID 39949834, 2025). "For instance, in human motor neurons carrying mutations that cause amyotrophic lateral sclerosis, a disease largely dependent on age, the most prominent IR event was observed in the SFPQ gene, which is involved in transcription and splicing." (PMID 38414808, 2024). "A member of another family of splicing factors, proline/glutamine-rich splicing factor SFPQ, is associated with amyotrophic lateral sclerosis, Alzheimer’s Disease and Frontotemporal Dementia." (PMID 30916337, 2019). "Intron retention and nuclear loss of SFPQ are molecular hallmarks of amyotrophic lateral sclerosis (ALS)." (PMID 31684996, 2019). "Some paraspeckle proteins, such as TDP-13, FUS, EWS, TAF15, HNRNPA1, SS18L1, and SFPQ have been associated with neuro-degenerative diseases, such as amyotrophic lateral sclerosis (ALS) and frontotemporal dementia (FTD)." (PMID 30087896, 2018). "Dysregulation of SFPQ is often observed in neurological disorders such as Alzheimer's disease (AD) and amyotrophic lateral sclerosis (ALS)." (PMID 39856764, 2025). "Altered expression and nuclear-to-cytoplasmic redistribution of SFPQ have been recognized in amyotrophic lateral sclerosis (ALS) pathology, yet the mechanistic bases for these phenomena remain undetermined." (PMID 40845103, 2025). "However, the mislocalization and cytoplasmic aggregation of SFPQ are associated with the pathophysiology of amyotrophic lateral sclerosis (ALS)." (PMID 36168806, 2022). "We recently described aberrantly increased cytoplasmic SFPQ intron-retaining transcripts (IRTs) and concurrent SFPQ protein mislocalization as new hallmarks of amyotrophic lateral sclerosis (ALS)." (PMID 33693641, 2021). "SFPQ is a key regulator of long neuronal gene expression and thus plays an important role in the pathogenesis of amyotrophic lateral sclerosis, frontotemporal lobar degeneration, and autism spectrum disorder, which are often caused by a dysregulation of the expression of long genes." (PMID 36674445, 2023). "In this context, it would be intriguing to note that a number of paraspeckle-enriched RBPs with IDRs, including SFPQ, FUS, EWSR1, TAF15, TDP-43, SS18L1 and HNRNPA1, are mutated in familial cases of amyotrophic lateral sclerosis (ALS) and other neurodegenerative diseases." (PMID 30355755, 2018). "Although not examined in a cancer context, an interaction between cyclin F and SFPQ is of clinical relevance to familial and sporadic amyotrophic lateral sclerosis (ALS) and frontotemporal dementia (FTD)." (PMID 40276932, 2025). "Furthermore, SFPQ mislocalization has been observed in neurodegenerative disorders such as Amyotrophic Lateral Sclerosis, Alzheimer’s and Frontotemporal dementia, where its functional loss could contribute to genome instability and neuronal vulnerability through similar RAD51-dependent mechanisms." (PMID 40964404, 2025). "These include TDP43, FUS, hnRNPA1, PSF/SFPQ and p54/NONO, all of which have been linked to neurodegeneration associated with amyotrophic lateral sclerosis and frontotemporal dementia." (PMID 29426953, 2018).
frontotemporal dementia (12 papers, 2012 to 2025). Frontotemporal dementia (FTD) comprises a group of neurodegenerative disorders, characterized by progressive changes in behavior, executive dysfunction and language impairment, as a result of degeneration of the medial prefrontal and frontoinsular cortices. "Studies have demonstrated that mice exhibit frontotemporal dementia-like behavior following the knockout of SFPQ in the hippocampus." (PMID 39949834, 2025). "SFPQ modulates the splicing of Tau, while Tau mediated the nuclear depletion of PSF/SFPQ in Alzheimer's and Pick's disease together with a cytoplasmic accumulation, as well as a depletion in the brain of Down syndrome cases." (PMID 27034888, 2016). "Specifically, SFPQ, a nuclear factor with a role in splicing and the regulation of gene expression, is depleted from the nucleus and forms cytoplasmic aggregates in tauopathies such as AD and Pick's disease." (PMID 24386422, 2013). "Importantly, SFPQ dysfunction has been linked to multiple cancers including ovarian, breast, and prostate malignancies; as well as neurodegenerative diseases, such as ALS and frontotemporal dementia." (PMID 40964404, 2025). "The neuronal RBP SFPQ, which is required to sustain long‐distance transcription elongation for longer genes, has a role in neurodegenerative diseases, including ALS, ASD, and frontotemporal lobar degeneration (FTLD)." (PMID 30988016, 2019). "Furthermore, spatial dissociation of nuclear SFPQ and FUS, which normally form a high–molecular weight (HMW) complex, causes increased four-repeat tau isoform expression, which, in turn, leads to frontotemporal dementia (FTD)–like phenotypes in mice and neurodegeneration in human cortical neurons." (PMID 40845103, 2025).
Alzheimer disease (9 papers, 2017 to 2025). A progressive, neurodegenerative disease characterized by loss of function and death of nerve cells in several areas of the brain leading to loss of cognitive function such as memory and language. "Nuclear depletion and cytoplasmic accumulation of SFPQ have been linked to the pathophysiology of neurodegenerative diseases, including Alzheimer's disease and ALS." (PMID 36168806, 2022). "Previous studies have identified cytoplasmic localisation of SFPQ in Alzheimer's disease patients, along with its colocalisation with p‐Tau." (PMID 39636149, 2024). "Previously, the downregulation of SFPQ is shown in Alzheimer’s disease (AD) patient’s brains, which contributes to the rapid progression of AD26." (PMID 34404863, 2021). "Microarray data analysis of transcripts in cortical neurons of Alzheimer’s disease (AD) patients identified upregulated SFPQ expression." (PMID 28392072, 2017). "The RNA-binding protein SFPQ plays an important role in neuronal development and has been associated with several neurodegenerative disorders, including amyotrophic lateral sclerosis (ALS), frontotemporal dementia (FTD), and Alzheimer’s disease." (PMID 33771997, 2021). "Cytoplasmic aggregates containing SFPQ and TIA1 have also been observed in an in vivo Alzheimer’s disease model." (PMID 38668381, 2024).
colorectal cancer (9 papers, 2016 to 2025). A primary or metastatic malignant neoplasm that affects the colon or rectum. "The interaction between HOTAIRM1 and SFPQ is a promising diagnostic biomarker of colorectal cancer." (PMID 30309340, 2018). "Knockdown of SFPQ in colorectal cancer cells was shown to enhance apoptosis, and multiple reports link SFPQ to altered transcriptional, transport and splicing profiles of mRNAs involved in cancer progression and drug resistance." (PMID 40276932, 2025). "For example, metastasis associated with lung adenocarcinoma transcript-1 (MALAT1), a functional long non-coding RNA highly expressed in colorectal cancer cells, promotes cell proliferation and migration by binding to SFPQ, thus releasing PTBP2 from the SFPQ/PTBP2 complex." (PMID 35006436, 2020). "Colorectal cancer growth and metastasis could be promoted by the release of oncogene PTBP2 from the SFPQ/PTBP2 complex, which is achieved by the affinity between human metastasis-associated lung adenocarcinoma transcript 1 (lncRNA MALAT1) and SFPQ." (PMID 32429086, 2020). "In colorectal cancer, MALAT1 could also bind to splicing factor proline and glutamine rich (SFPQ), thus increasing cell proliferation and migration." (PMID 30131454, 2018). "For example, In the investigation of colorectal cancer (CRC), MALAT1 could bind to SFPQ, thus releasing PTBP2 from the SFPQ/PTBP2 complex and the interaction between MALAT1 and SFPQ could be a novel therapeutic target for CRC35." (PMID 28623317, 2017). "A high expression of GAPLINC (Gastric adenocarcinoma predictive long intergenic noncoding RNA) promotes colorectal cancer invasion by binding to PSF (also known as SFPQ, splicing factor proline and glutamine rich) and NONO (non-POU-domain-containing, octamer binding)." (PMID 29416704, 2018).
prostate carcinoma (7 papers, 2010 to 2025). A carcinoma that arises from epithelial cells of the prostate gland. "Aberrant SFPQ function is associated with the aetiology of neurodegenerative disorders and colorectal, hepatocellular, renal, Chronic Myeloid Leukaemia and prostate cancer." (PMID 34218270, 2021). "The loss of SFPQ expression during the progression of prostate cancer may be an important key to understand this disease or one of its subtypes." (PMID 20805891, 2010). "Notably, SFPQ dysregulation has been reported in ovarian, breast, and prostate cancers, that also harbor recurrent mutations or altered expression of RAD51 family members, suggesting that disruption of this SFPQ–RAD51 axis may represent a shared vulnerability across these malignancies." (PMID 40964404, 2025). "SFPQ has been previously shown to regulate the stability of AR transcripts in prostate cancer and neurons and our own analysis of SFPQ-enriched transcripts identify SOX10 and the lncRNA, TMEM51-AS1 as being destabilised in SFPQ depleted cells." (PMID 34218270, 2021). "Expression levels of PTEN, HDAC1 and SFPQ hub proteins in Prostate Cancer (Cancer) and adjacent benign tissues (Benign)." (PMID 23737958, 2013). "SFPQ and NONO, belonging to DBHS family, are both pre-mRNA splicing factors and associated with tumorigenesis of multiple cancers such as prostate cancer and breast cancer." (PMID 36816933, 2023).
viral infection (7 papers, 2018 to 2024). "Some other associated host proteins were also found in some experimental studies assessing viral infection; for example, SFPQ was found to interact with the SARS-CoV-2 genome and promote viral RNA amplification." (PMID 36970680, 2023). "NEAT1 is induced by IAV infection, and this relocates SFPQ to the paraspeckle, thereby eliminating its transcriptional repression of interleukin-8 (IL-8) expression and thus activating an innate immune pathway in response to viral infection." (PMID 30429226, 2018). "Under viral infection conditions, lnc-EPAV competitively binds SFPQ, which dissociates SFPQ from the RELA promoter and promotes RELA expression." (PMID 39408810, 2024). "Since SFPQ/PSF is also an essential factor for influenza virus mRNA polyadenylation, NEAT1 is thus a dual regulator of viral infection through increasing the expression of antiviral genes and facilitating viral gene expression." (PMID 32543285, 2020). "SFPQ was additionally identified through the siRNA screen, along with the mRNA export factor, NXF-1, as being among the strongest proviral interactors (i.e. depletion of these factors inhibited viral infection)." (PMID 34019569, 2021).
colon carcinoma (5 papers, 2013 to 2025). "Recently, SFPQ has been identified as one of NORAD-interacting proteins in HCT116 colon carcinoma cells." (PMID 32267831, 2020). "PTB‐associated splicing factor (PSF), also known as splicing factor proline‐ and glutamine‐rich (SFPQ), is a PPARγ‐interacting protein involved in RNA processing and DNA repair process, and serves as a regulator of apoptosis in colon cancer cell lines." (PMID 32596958, 2020). "Furthermore, it has been found that SFPQ knockdown promotes apoptosis in human colon cancer cells, indicating that SFPQ influences cell apoptosis." (PMID 39949834, 2025).